CD44 (CD44 molecule (IN blood group))
Diseases named in the same sentence as CD44 in open-access papers (continued):
Sharing a sentence is not in itself a finding about the gene and the disease.
tumor (continued). "In the non-responder group, panCK, CD44 and CD66b were found to be the most differentially expressed proteins in the tumor compartment, while SMA and Fibronectin, and Pan-AKT were more highly expressed in the stroma." (PMID 37153589, 2023). "This proved not to be the case; the Cd44 gene status had no influence on the development of primary liver tumors in Nf2flox/flox;Alb-Cre mice, suggesting that deletion of Nf2 leads to tumor-promoting mechanisms independent of Cd44." (PMID 37174657, 2023). "Indeed, in the TSPO HIGH III cluster we observed a significant overexpression of the MES-like TAM tumor interaction genes OSM, OSMR, STAT3 and of CD44." (PMID 37697350, 2023). "Signal transduction from tumor cells of specific states (stress-like and hypoxia-like tumor cells) to PCs, for example, via the LAMB3/CD44 and ANGPTL4/SDC1 ligand/receptor pairs, was validated by spatial transcriptome analysis and associated with poorer OS as well as nonresponse to immunotherapy." (PMID 37138324, 2023). "Importantly, we measured higher percentage of effector circulating memory T cells (CD3+, CD8+, CD44+, CD62L-) and central memory T cells (CD3+, CD8+, CD44+, CD62L+) in the tumor draining lymph nodes of FLU-4T1+ICV mice following tumor re-challenge." (PMID 36860852, 2023). "Particularly, They show high expression of cell proliferation-related genes MKI67 and TOP2A, but tumor stem cell marker genes CD44 and CD133 were not highly expressed." (PMID 37880655, 2023). "Importantly, whereas endogenous CD44+CD8+ TILs mostly distributed across C4 (canonical TEX) and C2 (effector memory) at the time of tumor regression following PD1d/IL-2v/IL-33 ACT, the C5 TSE effector state identified above was a unique property of OT1 TILs." (PMID 37081150, 2023). "As potential reasons for this discrepancy, the authors suggested the molecular heterogeneity of GBM and the fact that the optimal cut-off values for CD44 expression had not been determined for each grade of tumor." (PMID 37835592, 2023). "Under hypoxic conditions, CD44-ICD binds to HIF-2α and activates HIF-2α expression, which further activates HIF-2α target genes, including cyclin D1, Nanog, Oct4, Sox2, and OPN, resulting in the promotion of tumor proliferation and stemness of GSCs." (PMID 37835592, 2023). "Surprisingly, grouped analysis of their expression levels in NJ115 tumoroids compared to the original tumor tissue showed a decrease in E-cadherin expression, lack of CD44+ progenitor-like cells and absence of cell proliferation." (PMID 37736770, 2023). "Therefore, we selected CD44 and CD24 as tumor cell stemness markers in GC and detected their expression." (PMID 37005676, 2023). "Histological evaluation of qMCP-deficient and WT tumors showed reduction of tumor-associated macrophages by IBA1 staining with no changes in P2RY12, CD31, OLIG2, GFAP, and CD44 positive areas." (PMID 37012245, 2023). "Under steady-state conditions, HMW-HA (>500 kDa) is the dominant HA size in most tissues and inhibits tumor progression, while LMW-HA (<120 kDa) may regulate tumor growth, invasion and metastasis through HA receptors in TME, such as CD44 and RHAMM." (PMID 36936902, 2023). "In the tumor-draining lymph nodes, CD4+ T cell depletion or its combination with PD-L1 blockade therapy significantly elevated the proportions of CD44+CD69+CD8+, as well as central memory CD44+CD62L+CD8+ and effector memory CD44+CD62L−CD8+ T cells." (PMID 36969495, 2023). "CD44-positive CSCs exhibit enhanced tumorigenic potential, forming tumours more efficiently in xenograft models of different cancer types, compared to CD44-negative cells." (PMID 37958796, 2023). "For protection, P-selectin, a cubicle adhesion scintilla upregulated in activated PLTs, ass group to P-selectin glycoprotein ligand-1 (PSGL-1) or CD44 overexpressed on tumor cells, thereby allowing complex and dynamic PLT–tumor cross-talk critical for tumor growth and metastasis." (PMID 38129881, 2023).
tumor (continued). "Overall, the CD44/CD24 cell distribution in TNBC cells was significantly altered across the surface topographies examined, strengthening the importance of mechanical stimuli in modulating tumor stemness cell ratios." (PMID 36968199, 2023). "It is well known that both CD44 and HIF contribute cancer stemness in the tumor microenvironment." (PMID 37064130, 2023). "Moreover, mRNA detection results of tumor tissues showed that vitamin C treatment significantly decreased the expression of VCAM-1, Vimentin, CD31 and CD44." (PMID 37283769, 2023). "The tumor tissue was digested into single cells and labeled with CD24 and CD44 antibodies." (PMID 36707875, 2023). "CD44 and CD54 are widely expressed in tumor, stromal, and immune cells." (PMID 37612301, 2023). "After sorting CD44-high and CD44-neg populations from 7 days KPY organoids, we transplanted the same number of cells from each population by intratracheal instillation, and the mice were euthanized two months after transplantation to quantify the tumor burden." (PMID 36993454, 2023). "In contrast, clear CD44+CD104low subpopulations were observed in the M13HS-2 and -8 tumor hybrids." (PMID 38139138, 2023). "The main finding of our study is that the close margin, defined as tumor-free by the conventional histopathological examination, may show high levels of SOX2, CD44, and CXCR4 to an extent comparable to that observed in the relative tumor core." (PMID 38096163, 2023). "Moreover, CD44-HA interaction activates downstream signaling pathways, such as the PI3K/Akt and MAPK/ERK, which promote tumor cell proliferation and survival." (PMID 37366874, 2023). "Various glycosaminoglycans (hyaluronic acid, heparin) and proteoglycans (CD44, CSPG4, MUC-1) have been suggested as potential cancer targets due to their important roles in tumor pathogenesis and their upregulation in malignant tissues but are also expressed in healthy tissues." (PMID 37118819, 2023). "In addition, CD29, CD44, CD146, CD81, C1Qa, and histone H3 were also recently identified as potential protein markers for the tumor progression of GB." (PMID 38074665, 2023). "Consequently, we investigated the relationship between degree of tumor invasiveness based on 5-ALA intensity and levels of CD44 expression (P/C ratio)." (PMID 37760811, 2023). "We demonstrated that GCEPs have self-renewal capacity, tumor formation capacity, and differentiation potential in vitro, thereby producing cells with different surface markers derived from single cells with the CD24+CD44+CD54+EpCAM+ phenotype." (PMID 36737794, 2023). "Additionally, tumor cells expressing elevated levels of the reported CSC markers NRP1, IGF1R, CD44, and PROM1 (CD133) were scattered across several clusters." (PMID 37966117, 2023). "Thus, there is a substantial body of scientific literature reporting that CD44 is a cancer stem cell (CSC) marker, and functions as a key regulator of cancer stemness, self-renewal, tumor initiation, and metastasis." (PMID 37005380, 2023). "Moreover, DR5 expression was also related to the expression of MKI67 and CD44, and stemness index (mRNAsi), which revealed the correlation between DR5 and tumor stemness." (PMID 37879960, 2023). "Cell populations expressing or not CD44-positive cells were sorted out by flow cytometry and detected by Western Blot and RT-qPCR for the tumor stemness markers OCT4 and SOX2." (PMID 37980488, 2023). "Treatment with 4-Methylumbelliferone (4-MU), which inhibits HA synthases, blocked HA accumulation in the ECM, decreased CD44 activation, resulted in diminished PI3K, AKT, and ERK signaling, and led to proapoptotic, antiproliferative, and antimetastatic effects in cultured tumor cells." (PMID 36766747, 2023). "In contrast, stem cells do not express the commonly expressed canonical CD44 isoform and do not promote tumor formation, indicating isoform-specific functions of CD44 in ISCs and tumorigenesis." (PMID 38130953, 2023).
tumor (continued). "Western blot and RT-PCR experiments also suggested that TRIM58 silencing tend to increase the stem-like cellular phenotype of these tumor cells, as both protein and mRNA expression of stem-cell marker ALDH1 and CD44 demonstrated notably increase in tumor cells treated by TRIM58 shRNAs." (PMID 36644609, 2023). "The present study demonstrates that high CD44 expression in the tumor periphery correlated with HI-type GBM, in which tumor invasiveness was evaluated by the specific features on MRI, whereas CD44 expression in the tumor core tended to be lower in HI-type tumor." (PMID 37760811, 2023). "We evaluated the stem cell signature in these patient-derived organoids and found significantly varying levels of stemness, especially in levels of CD44, nestin, and CD133 in our representative example patient tumor after receiving chemotherapy and radiation treatment." (PMID 37444398, 2023). "To determine whether CAF enrichment in tumor-bearing SVZ was related to GSC enrichment in this area, we performed qPCR on biopsies of SVZ-containing GBM versus tumor core and found unchanged expression of GSC markers nestin or CD44 (P = 0.1)." (PMID 36856115, 2023). "The group treated with non-conjugated nanocarriers showed lower expression of CD133 and EpCAM and no expression of CD44 cells in tumor." (PMID 37149607, 2023). "First, we demonstrated that adipocyte CM could exert a significant pro-tumor activity on PCa cells, by endowing them with CSC properties; specifically, it could promote tumor sphere formation as well as CD133 and CD44 upregulation." (PMID 36940071, 2023). "The protein levels of UHRF1, GLI1, CD133, and CD44 displayed similar expression patterns in HCC tumor and paired nontumor tissues, and overexpression (defined as a twofold increase in tumor) of these proteins was observed in nearly 50% of the samples." (PMID 37380646, 2023). "In the future, utilizing these methods of evaluation with CD44 and 5-ALA fluorescence spectroscopy may identify more useful markers for quantitatively and conventionally predicting tumor invasiveness in GBM." (PMID 37760811, 2023). "CD44+EpCAM (high) cells sorted from AGS cells subjected to gain-of-function experiments, followed by evaluation of their capacity of colony formation, generation of tumorosphere, cell migration and viability in vitro and xenograft tumor formation in vivo." (PMID 36765401, 2023). "In addition, when looking at the tumor-draining lymph node, there were more TRP2-specific CD8+ T cells that were positive for the canonical central memory markers CD62L and CD44 in mice cured by the combination therapy versus the 10-μg CBD–IL-12 monotherapy." (PMID 38019919, 2023). "To explore the capability of the CD44-targeted nanoagent DXBTZ-CB /CSA to detect tumors by means of multispectral optoacoustic imaging, we first established a mouse model of subcutaneous tumor by injecting MDA-MB-231 cells onto the back of mice." (PMID 37400468, 2023). "Unlike mesenchymal samples, the majority of hEMT tumours (20%) were characterised by both hypoxia and CD44 expression." (PMID 36774358, 2023). "In particular, CD44, a cell surface marker often upregulated in cancer stem cells (CSCs), was overexpressed in CTM, which is involved in the maintenance of stemness signaling in numerous tumor cell types." (PMID 36929453, 2023). "Moreover, the anti-tumor activity of CBS/H2S axis was largely attributed to the inhibition of a pivotal stem cell marker, CD44." (PMID 35172821, 2022). "We also analyzed CD44 expression in OSCC patients via the Oncomine database, revealing that the CD44 expression level was higher in OSCC tumor tissues compared to non-cancerous controls (p = 0.002)." (PMID 35629265, 2022). "Therefore, the potential target FRGs, SLC1A5, CD44 and NQO1, for tumor resistance treatment have important research value in the treatment of SCC drug resistance." (PMID 35501667, 2022).
tumor (continued). "Contrarily, an in vitro model of triple-negative breast cancer showed, that starvation (low serum, low glucose) reduced the proportion of CD44+ and ALDH-1+ stem cells, and in tumors transplanted to mice, it slowed down cancer growth and initiated tumor cell apoptosis." (PMID 36612107, 2022). "Studies on pancreatic cancer SP cells revealed that, at less than 1000 cells, tumor formation was initiated in nude mice, but that both non-SP cells and SP cells contained CD44+CD24+ and CD133+ cells." (PMID 35562905, 2022). "Our results indicated opposite expression patterns for MAL and CD44 in matched primary tumor samples, indicating a negative correlation in vivo." (PMID 35093120, 2022). "One of the most common CSC prognostic markers widely reported in CRC is a cluster of differentiation 44 (CD44), which regulates matrix metalloproteinases 7/9 (MMP7/9) to promote tumor progression and metastasis; however, the molecular role of CD44 in CRC is still unclear." (PMID 35203586, 2022). "Additionally, a positive correlation between the expression of MRE11 and CD44, or that of CD44 and phosphorylated AKT, was observed in OSCC tumor tissues." (PMID 35629265, 2022). "Comprehensive analyses of flow cytometry and immunohistochemistry results revealed that bevacizumab treatment enhanced the HIF-1α expression and increased the proportion of CD44+/CD117+ cells, resulting in the tumor recurrence in both the bevacizumab alone and bevacizumab + cisplatin groups." (PMID 36046821, 2022). "In breast cancer, CSCs express CD44+/CD24−/low/linage− stem cell-phenotype and are able to form mammospheres in suspension culture, differentiate into defined progenies, initiate and drive tumor growth in vivo." (PMID 36233074, 2022). "In addition, IHC staining demonstrated that downregulation of FAM64A decreased the expression of Ki-67, CD44, and SOX2 in tumor tissues." (PMID 35538067, 2022). "The transfer of CD44 to the nucleus is considered to be one of the important mechanisms of metastasis in many diseases, including tumours, and the partial CD44 ICD or even full‐length CD44 can act as a signal to transfer to the nucleus and regulate gene expression." (PMID 35146909, 2022). "Likewise, qPCR analysis suggested higher expression levels of CD44, CD133, ALDH1A1, and EpCAM in tumor hybrids than in HepG2 parental cancer cells." (PMID 35562905, 2022). "Interestingly, the CD44+CD133+ and ΔCD44+CD133+ subpopulations of Caco-2 cells displayed similar sensitivity to Juglone, although tumor-initiating cells generally show resistance, or lower sensitivity, to chemotherapeutic drugs." (PMID 35433695, 2022). "T cells infiltrating KPAR tumours were alsomore activated, with a higher proportion of effector memory CD8+ andCD4+ T cells andincreased expression of the activation marker CD44 on both CD8+ andCD4+ T cells as well as the early activation marker CD69 onCD8+ T cells." (PMID 35930804, 2022). "Further measuring the markers related to the tumor formation ability in mice subcutaneous tumors, we found that EpCAM, CD13, CD24, CD44, CD90 and CD133 in ZNF334-OE cells was significantly lower than that of the control group, which was consistent to the phenotype of the mice model." (PMID 35534462, 2022). "The HH and Wnt pathways can jointly induce CSC biomarkers, such as CD44, CD133, BMI1, and LGR5, and promote EMT, thereby promoting tumor cell infiltration and distant metastasis and allowing tumor cells to obtain stem cell characteristics and drug resistance capacity." (PMID 35719973, 2022). "Specifically, a very low number of CD44+/CD24− cells (100 cells) can form the tumor, whereas up to 10,000 non CD44+/CD24− cells failed to form tumors in NOD/SCID mice." (PMID 35631492, 2022).
tumor (continued). "BZM no longer has anti-metastatic activity after CD44 knockdown in sLeA/X-negative tumor cells or E-selectin knockout in mice." (PMID 35031433, 2022). "Blood was then collected starting at three weeks post tumor cell implantation and analyzed for FR positive and CD44 negative CTCs." (PMID 35595733, 2022). "The effects of h4#147D administration on protein expression of CD147, its binding partners, CD44, integrin α3, integrin α6, and MCT1, and downstream signaling molecules were analyzed using tumor samples derived from the MIA PaCa-2 xenograft model by protein capillary electrophoresis." (PMID 36385956, 2022). "In addition, CD44 also phosphorylates ERK/MAPK and RAS/MAPK signalling pathway to promote tumour angiogenesis, migration, and invasion." (PMID 36505828, 2022). "Total CD44 expression was higher in tumor tissue compared with paired non-invaded peritumor samples in 47 cases (78.95%)." (PMID 36291969, 2022). "Spatial proximity and co-localization of the receptor-ligand interaction pair CD44-HGF could be confirmed in the original tissues by immunofluorescence staining, supporting the in vivo relevance of tumor-stroma interactions occurring in our co-culture model." (PMID 36273171, 2022). "We found strong interactions between tumor cells and TAM populations mediated by macrophage migration inhibitory factor (MIF) and its receptors (CD44 and CD74), which have been well characterized to play vital roles in tumor progression, angiogenesis, and immune escape in ccRCC70–72." (PMID 35853872, 2022). "Among them, HA can actively target the overexpression of CD44 protein in tumor cells, and combined with the passive targeting of nanoparticles (EPR effect), the double targeting ensures that polymer micelles are taken up by tumor cells." (PMID 35261298, 2022). "Furthermore, we found that tumor-specific SPP1+ macrophages were a crucial component of intratumor heterogeneity, and that SPP1/CD44-mediated crosstalk played an important role in GC progression." (PMID 36612160, 2022). "Moreover, G9668 treatment led to significantly greater numbers of tumor-infiltrating cytotoxic CD8+ T cells and higher expression by these cells of the activation markers granzyme B, PD-1, and CD44." (PMID 35446348, 2022). "The paradigm of early metastasis with a consistent proportion of primary tumor cells enriched with high CD44, and low CD24 (high CD44/low CD24) stem cell-like features carries the potential to migrate primary tumor sites and form metastatic colonies in distant sites." (PMID 35736645, 2022). "They found that interactions between CD44 and MMP9 promoted the proteolytic activity of MMP9 against type IV of collagen, which correlated with cell invasiveness and enhanced tumor growth in vivo, and disruption of the CD44–MMP9 complex reduced the migratory potential of cancer cells." (PMID 35406619, 2022). "In contrast, no increase was observed in the presence of CD44-/- microglia (73.91 ± 12.42) confirming that the tumor invasion promoting effect of myeloid cells is CD44-dependent." (PMID 35992852, 2022). "Moreover, combination therapy increased the effector CD44+ CD8+ PD1- subset and decreased the proportion of terminally-differentiated CD103+ KLRG-1+ T-regulatory cells on both sides of tumor." (PMID 36513720, 2022). "Clearly, both WB and IF showed that shRNA silencing CXCR4 synergistically enhanced the effect of PTX treatment on decreasing Akt phosphorylation and the resulting reduction in N-cadherin, vimentin, snail, CD44, CD133, and NANOG protein expression in OVCA420 tumor tissues." (PMID 35681259, 2022). "Pursuing this line of research, we examine here the possibility that CD44 could directly contribute to TF regulation and thereby modulate coagulant activity on EMT+ tumor cells." (PMID 35805061, 2022).